ZNF691 (zinc finger protein 691)
Description:
May be involved in transcriptional regulation.
Synonyms: Zfp691
Tractability: PROTAC: UniProt records ubiquitination sites on it.
Gene: Protein-coding gene on chromosome 1 (42,846,573 to 42,852,477, forward strand). Ensembl gene ENSG00000164011.
Subcellular location: Nucleus
Subcellular location (Human Protein Atlas): Nucleoplasm; Nucleoli; Vesicles
Pathways (Reactome):
Gene expression (Transcription): Generic Transcription Pathway
Gene Ontology:
Molecular function: protein binding; DNA-binding transcription factor activity; RNA polymerase II cis-regulatory region sequence-specific DNA binding
Biological process: regulation of transcription by RNA polymerase II
Cellular component: nucleus
Genetic constraint (gnomAD): Loss-of-function variants: 11 observed, 25.01 expected, observed/expected ratio (o/e) 0.44, 90% interval 0.28 to 0.73. The upper end of that interval is the gene's LOEUF score, 0.73, which puts it in group 2 of 6, group 1 being the genes least tolerant of losing a copy. Missense variants: 356 observed, 427.97 expected, observed/expected ratio (o/e) 0.83, 90% interval 0.76 to 0.91. Synonymous variants: 149 observed, 161.53 expected, observed/expected ratio (o/e) 0.92, 90% interval 0.81 to 1.06.
Homologues: Orthologues: chimpanzee ZNF691 (99% identical), macaque ZNF691 (93% identical), dog ZNF691 (83% identical), rabbit ZNF691 (80% identical), pig ZNF691 (77% identical), mouse Zfp691 (77% identical), guinea pig ZNF691 (77% identical). Paralogues in human: ZSCAN20 (46% identical), ZSCAN2 (42% identical), ZNF256 (36% identical), ZNF480 (35% identical), ZNF551 (35% identical), ZNF583 (35% identical), ZNF79 (35% identical), ZNF793 (34% identical), ZNF792 (34% identical), ZNF304 (33% identical), ZNF660 (33% identical), ZNF549 (32% identical), and 26 more.
Diseases named in the same sentence as ZNF691 in open-access papers:
ZNF691 is named in the same sentence as 3 diseases in open-access papers, as found by Europe PMC text mining. Sharing a sentence is not in itself a finding about the gene and the disease. The quoted sentences say what the papers report.
Bovine mastitis (1 paper, 2023). INFLAMMATION of the UDDER in cows. "For many of the genes that overlapped with dMHB discriminant signatures in this study, such as ZNF691, MAML2, ZC2H7B, CD101, TSPAN32, and MAML2, this is the first report of their involvement in bovine mastitis." (PMID 37373515, 2023).
ovarian carcinoma (1 paper, 2019). A malignant neoplasm originating from the surface ovarian epithelium. "In summary, using a functional genomics screen, we identified six novel genes, MSL3, ZNF691, VPS45, ITGB3BP, TLE2, and ZNF498, that regulate the proportion of SP cells in ovarian cancer." (PMID 31578411, 2019). "In this study, we identified six novel genes, MSL3, ZNF691, VPS45, ITGB3BP, TLE2, and ZNF498 whose expression altered the proportion of the SP cells of ovarian cancer cells through a functional genomics screen." (PMID 31578411, 2019). "In conclusion, through a functional genomics screen using an shRNA library we identified six novel genes; MSL3, ZNF691, VPS45, ITGB3BP, TLE2 and ZNF498, whose downregulation individually increased the proportion of SP cells and the malignant phenotypes of ovarian cancer." (PMID 31578411, 2019). "In ovarian cancer cases, low expression of MSL3, ZNF691 and VPS45 was related to poor prognosis." (PMID 31578411, 2019).
infection (1 paper, 2024). The state of being infected such as from the introduction of a foreign agent such as serum, vaccine, antigenic substance or organism. "We further identify several TFs which are not, in healthy cells, specific to any immune cell type, but are predicted to have cell type-specific changes to TF activity during infection (e.g., HMBOX1, ZNF24, ZNF691)." (PMID 38238840, 2024).